VIM (vimentin)
Diseases named in the same sentence as VIM in open-access papers (continued):
Sharing a sentence is not in itself a finding about the gene and the disease.
melanoma (continued). "In agreement with our observations, WNT5a has been shown to increase Vimentin and CD44 to enhance motility of melanoma cells and nasopharyngeal carcinoma via the Ca2+ signaling pathway." (PMID 32546756, 2020). "Biomechanical analysis, as well as F-actin and vimentin staining have shown that both low-LET proton beam and X-rays induced higher elasticity due to perturbed cytoskeleton in melanoma cells." (PMID 31065009, 2019). "Moreover, Exo facilitate the EMT of melanoma cells consisting of the acquisition of the mesenchymal phenotype and pro-invasive behavior by up-regulating Let7a, Let7i, and miR-191, which, in turn, down-regulate E-cadherin and activate the expression of vimentin, ZEB2, and SNAIL2." (PMID 31861757, 2019). "In the current study, we found that melanoma cells augmented the expression of various mesenchymal phenotypic markers, such as Smad2/3, α-SMA, and vimentin, in addition to that of TGF-β, Snail, and Slug, following exposure to Tregs." (PMID 31690033, 2019). "Immunochemical analysis revealed positivity for vimentin, S100, and HMB-45 (human melanoma black 45), a result compatible with a diagnosis of malignant melanoma." (PMID 28255482, 2017). "The transcripts of 6 significantly changed proteins (VIM, DNM1, SMARCC2, CSDE1, EIF4A2 and ANXA2) have been previously identified as direct RNA targets of CSDE1 in human melanoma cells." (PMID 29129916, 2017). "In contrary, the expression of vimentin, a mesenchymal marker of cells undergoing EMT during metastatic progression, was upregulated in melanoma cells." (PMID 27061029, 2016). "Among these possibilities, malignant melanoma is positive for HMB-45 and ectopic meningioma is positive for vimentin and EMA." (PMID 25435998, 2015). "Our results demonstrate that carnosic acid downregulated the mesenchymal markers vimentin and N-cadherin and upregulated the epithelial marker E-cadherin, indicating that carnosic acid inhibits the EMT in B16F10 melanoma cells." (PMID 25036034, 2014). "Of particular interest is the substantial decrease (2.3×) in vimentin, a marker of EMT and of the metastatic properties of melanoma." (PMID 24392146, 2014). "Conversely, Ad-HDGF shRNA infection potentiated protein level and the promoter activity of E-cadherin, and reduced the protein levels of vimentin and α-SMA in B16–F10 melanoma cells." (PMID 23536873, 2013). "Western blot showed that exogenous rHDGF (10 ng/mL) treatment significantly reduced the protein level of E-cadherin, an epithelial marker, while it elevated the protein levels of mesenchymal markers, including vimentin and α-SMA in melanoma cells." (PMID 23536873, 2013). "Our finding reveals that E-cadherin protein level is down-regulated, whereas vimentin and α-SMA are up-regulated in HDGF-treated melanoma cells." (PMID 23536873, 2013). "We also show that HDGF modulates EMT changes by down-regulating E-cadherin and up-regulating vimentin and α-SMA, which contributes to tumor cell invasion and metastasis in melanoma in vitro and in vivo." (PMID 23536873, 2013). "We observed Dbait32Hc-induced vimentin phosphorylation on Ser459 in mouse embryonic fibroblasts (MEF, in 38% of transfected cells) or murine melanoma cells (B16BL6, in 50% of transfected cells)." (PMID 24282534, 2013). "We had found HSP60 and aconitase also for melanoma, and HSP 71, vimentin and tubulin had been reported for other cancers." (PMID 20020065, 2009). "Furthermore, WAY-316606 markedly impaired the migratory and invasive capacities of metastatic melanoma cells, accompanied by downregulation of key ECM remodeling and fibrosis-related genes, including VIM, CCN2, FN1, and TGFBI." (PMID 42279305, 2026). "Diagnosis was established based on morphology and strong nuclear TFE3 immunoreactivity, supported by additional immunohistochemical (IHC) markers including cluster of differentiation 10 (CD10), Melan-A, human melanoma black 45 (HMB45), vimentin, carbonic anhydrase IX (CAIX), and cytokeratins." (PMID 42220779, 2026).
melanoma (continued). "Interestingly, in melanoma, it has been demonstrated that protein kinase C-iota (PKC-ι)-induced EMT concurrently upregulated vimentin expression." (PMID 40332096, 2025). "Western blot analysis demonstrated increased levels of pro-apoptotic cleaved caspase-3 (c-caspase-3) and epithelial marker E-cadherin, alongside decreased levels of anti-apoptotic Bcl-2 and mesenchymal marker Vimentin, reinforcing the oncogenic function of COL11A2 in melanoma." (PMID 40574832, 2025). "Our findings showed that the knockdown of SLNCR1 resulted in the suppression of Ki67 and Vimentin expressions, suggesting that SLNCR1/SOX5 axis may promote melanoma growth in vivo via the regulation of the EMT pathway." (PMID 38561355, 2024). "Simple Western analysis was performed to confirm PLK1 overexpression in melanoma cells and its effect on EMT markers, which showed an increasing trend in the expression of mesenchymal markers, such as N-cadherin and Vimentin, as well as transcription factors ZEB1 and SNAIL." (PMID 38184733, 2024). "In CF groups, the expressions of Integrin and Vimentin of B16F10 cells on matrix were significantly higher than other groups, suggesting that matrix seemed to be able to enhance the Integrin‐mediated intercellular crosstalk of VM in melanoma." (PMID 39036079, 2024). "Mucosal melanoma histopathological findings are most commonly positive for S-100 and vimentin, occasionally positive for human melanoma black-45 (HMB-45) and Melan-A, and usually negative for cytokeratin and epithelial membrane antigen." (PMID 39006602, 2024). "Vimentin, SNAL1, and MMP2 are essential genes for melanoma EMT." (PMID 39135915, 2024). "E-cadherin and GSK-3β were up-regulated whereas vimentin and β-catenin were downregulated in si-LINC00662 melanoma cells, and si-LINC00662 can also reduce the levels of β-catenin protein in the nucleus which might affect β-catenin transcriptional activity." (PMID 38169586, 2024). "For instance, benign granular cell tumors are positive for S-100 protein, CD63, CD68 and neuron-specific enolase whereas atypical fibroxanthoma stains negatively for S100 protein, Melan-A, human melanoma black (HMB)-45 pan-cytokeratin (CK) and actin and positively for CD68 and vimentin." (PMID 36832159, 2023). "Vimentin is a canonical marker of EMT and its high expression, similarly to YB-1, has been shown to induce a highly motile, invasive phenotype in melanoma." (PMID 39086667, 2023). "As per the IF staining results, fibroblasts cocultured with the melanoma spheroids (coculture) formed thick actin stress fibers, exhibiting an increased expression of alpha‐smooth muscle actin (α‐SMA) and the stromal marker vimentin." (PMID 36026581, 2022). "Multiple studies have confirmed the strong immunoreactivity of Fuchs’ adenoma cells to S-100 moderate immunoreactivity to vimentin and cytokeratin, with negative reactivity to melanoma-specific HMB45, confirming the origin as nonpigmented ciliary epithelial." (PMID 35365243, 2022). "However, in the present study, we indicated that TLR4 was a ligand of PA, which promoted the lung metastasis of melanomas by activating TLR4 as well as the nuclear translocation of pNF-κB, influencing the translation of E-cadherin, MMP2, and Vimentin." (PMID 36422271, 2022). "We found that YY1-knockdown melanoma cells were more sensitive to TGF-β1 stimulation, in that YY1 knockdown cells treated with TGF-β1, boosted the expression of the EMT genes FN1, CDH2, ZEB1, SNAI1 and VIM, among others." (PMID 35693944, 2022). "Staining for vimentin, however, showed positivity in 9/9 reported rhabdoid primary melanomas and was not done in one primary tumor." (PMID 35645230, 2022).
melanoma (continued). "CAFs were isolated from a cutaneous MM biopsy and were characterized: cells showed a spindle-shape and flattened morphology, and were strongly positive for vimentin and PDGFRβ according to the literature but were negative for the melanoma marker Melan-A." (PMID 34638245, 2021). "Staining is positive for CD68 and vimentin and negative for Melan-A, human melanoma black (HMB)-45, S100 protein, pan-cytokeratin (CK), and actin." (PMID 34449582, 2021). "Markers, including vimentin, S-100 protein, neuron-specific enolase (NSE), Melan A, PNL2, human melanosome-specific antigens -1 (HMSA-1), and HMSA-5 have been assessed for their potential in aiding the diagnosis of canine malignant melanoma." (PMID 34822634, 2021). "The same study also found the upregulation of vimentin, fibronectin, and α-SMA and downregulation of E-cadherin in EIF5A2-overexpressing melanoma cells, suggesting that EIF5A2 might induce EMT." (PMID 32605067, 2020). "We observed in benign nevi and normal skin tissues that vimentin-expressing stromal cells expressed ATF3 (stained red, white arrow heads), while the majority of vimentin+ cells in malignant melanoma did not express detectable ATF3 (white arrows)." (PMID 32373541, 2020). "When HopQ was expressed in melanoma cell, its N-terminal portion bound to 14-3-3, which increased the binding of HopQ to vimentin, whereas no changes in the established 14-3-3 signaling pathways were observed." (PMID 32286254, 2020). "It is assumed that melanoma can metastasize faster than other malignant skin tumors, being more aggressive because normal melanocytes possess from the start elements which contribute to EMT, such as vimentin or some transcription factors (SNAIL2, ZEB2)." (PMID 31934531, 2019). "Decreased HIF1α activity by RNA interference significantly inhibited E-cadherin expression and increased Vimentin expression, and reversed the process of EMT, suggesting that HIF1α may be a new target to treat melanoma metastasis." (PMID 31371307, 2019). "Along with higher cell elasticity, BLM cells also exhibited a higher level of vimentin (after X-rays at 20 days and low-LET proton beam at 40 days), which may suggest the possibility of EMT transition switching phenotype in melanoma cells post-radiation." (PMID 31065009, 2019). "Indeed, we found decreased collagen, fibronectin and vimentin content in the cocultured spheroid stroma, suggesting that there were changes in ECM dynamics and organization that influenced cellular behaviors of melanoma cells." (PMID 31885878, 2019). "Vimentin and S100 seem to be highly specific for malignant melanoma, whereas HMB45 is not and is also overexpressed in malignant angiomyolipoma of the liver and pulmonary lymphangiomyomatosis." (PMID 28865487, 2017). "We also studied human melanoma datasets from The Cancer Genome Atlas (TCGA), and found that the TET proteins, especially TET2 were downregulated, and the mesenchymal marker Vimentin and EMT master transcription factors like ZEB2, SNAIL2 and TWIST1 were up regulated." (PMID 27852070, 2017). "Levels of E-cadherin and vimentin expression did not correlate with the clinicopathological features of SCC or melanoma." (PMID 26894856, 2016). "Melanoma cells overexpressing UBE3C frequently exhibited a mesenchymal phenotype, including reduced expression of the epithelial marker E-cadherin and expression of the mesenchymal marker vimentin." (PMID 26894856, 2016). "On the basis of these findings, we speculated that enforced miR-200c expression in melanoma B16F10 cells profoundly impairs cell tumorigenicity and phenotype change of EMT along with significantly decreased expression of TGF-β, Vimentin, ZEB-1and N-cadherin." (PMID 24625224, 2014). "Similarly, HDGF overexpression by Ad-HDGF gene delivery reduced the protein level and promoter activity of E-cadherin, while it elevated the protein levels of vimentin and α-SMA in B16–F10 melanoma cells." (PMID 23536873, 2013).
melanoma (continued). "In our two cases, immunohistochemical staining demonstrated that the tumor cells expressed HMB45, S-100, pan melanoma and Vimentin, and did not express CK, EMA, CgA, Syn, HCG, HMW-CK, Desmin, SM-actin, TTF-1, and SCLC." (PMID 22992473, 2012). "Multifocal melanoma liver metastases were identified by lack of expression of cytokeratin, cytokeratin 19 and the expression of Melan A and vimentin." (PMID 23009723, 2012). "The immunohistochemistry has referred positivity in a varying level for the antigens related to the melanoma: NKI/C-3, S-100 protein, gp100 (HMB-45), Mart-1 (Melan-A), vimentin, tyrosinase and microphthalmia transcription factor (MiTF) that are useful in the diagnosis." (PMID 22143709, 2012). "So we presume that vimentin should have special biological features in melanoma hematogenous metastasis, not involving in lymph node metastasis." (PMID 20701774, 2010). "We demonstrated that the EVs derived from adipocytes did not alter melanoma cell proliferation but significantly promoted tumor cell migration and invasion by determining an enrichment in mesenchymal markers, such as N-cadherin and vimentin." (PMID 41897479, 2026). "Vimentin is a key EMT biomarker present in mesenchymal cells and usually overexpressed during cancer metastasis, while MMP-2 and MMP-9 are peptidases involved in extracellular matrix remodeling and tumor invasive processes, favoring melanoma spreading and metastasis." (PMID 39981176, 2025). "Comparative analyses between tumor-associated keratinocytes (TAKs) and normal keratinocytes (NKCs) from tissue without melanoma revealed upregulation of EMT markers vimentin and N-cadherin in TAKs, confirming the EMT-like morphological changes of keratinocytes in our imaging results." (PMID 39229155, 2024). "Interestingly, in YB-1 melanoma knock-out cell line, nestin was nearly absent and vimentin was expressed at significantly lower levels." (PMID 39086667, 2023). "In the literature sinonasal INI1-deficient carcinoma had immunohistochemically diffused expression of cytokeratins (CK), p16, p40, and p63 in all cases, while expression of CK5/6, CK7 and vimentin was only focal or absent, and the diagnosis of melanoma was definitively excluded." (PMID 37974295, 2023). "However, it could be excluded the possibility of perivascular epithelioid cell tumors and malignant melanoma with sarcomas because of the negativity of immunohistochemical staining for HMB-45 and vimentin." (PMID 36140448, 2022). "Moreover, we found that in acidic female melanoma cells, in which the ERβ expression increase correlates with an unaltered level of N-cadherin and vimentin, invasiveness does not change." (PMID 36499700, 2022). "Vimentin, an EMT marker and major component of the cytoskeleton in mesenchymal cells, also showed higher expression level in the A375LM3IF4g/Luc and A375LM5IF4g/Luc melanoma cells (2.6- and 2.2-fold, respectively) than in parental A375 and A375IF4g/Luc cell lines." (PMID 33810045, 2021). "The gain of invasive capability was also associated with an increased expression of EMT genes (e.g., CDH2, FN1, VIM, SNAI1), as revealed by both RT-qPCR and WB analyses of bulk tumors, Bdmc+/+ and Bdmc−/− cells and siAMBRA1 human melanoma SK-Mel-5, MeWo and SK-Mel-2 cells." (PMID 33953176, 2021). "We found that TAP7f downregulated the expression of Snail and the mesenchymal markers vimentin and N-cadherin and increased expression levels of E-cadherin, suggesting that the anti-metastatic effect of this synthetic compound is also mediated by the inhibition of EMT in melanoma cells." (PMID 32158394, 2020). "Another lncRNA (SPRY4-IT1) was identified as a regulator of both apoptosis and differentiation in melanoma, while further study in non-small cell lung cancer (NSCLC) also revealed a possible role in the activation of the EMT machinery by regulating both E-cadherin and vimentin expression." (PMID 31861757, 2019).
melanoma (continued). "The miR-200 family, moreover, is considered of particular relevance for the metastatic process of melanoma cells, since it drives the EMT process by negatively influencing the zinc finger E-box-binding homeobox 1 (ZEB1) and E-Cadherin, while stimulating the expression of N-Cadherin and vimentin." (PMID 31861757, 2019). "Vimentin is a nonspecific marker; however, a vimentin-negative tumour is unlikely to be a sarcoma (with the exception of alveolar soft part sarcoma), lymphoma, or melanoma." (PMID 29621151, 2018). "Moreover, nifuroxazide markedly impaired melanoma cell migration and invasion by down-regulating phosphorylated-Src, phosphorylated-FAK, and expression of matrix metalloproteinase (MMP) -2, MMP-9 and vimentin." (PMID 26830149, 2016). "The ability of PARP inhibition to modulate vimentin levels (and hence EMT), the interference with vasculogenic mimicry, and the modulation of endothelial plasticity allowed PARP inhibitors to exert a multifaceted antimetastatic effect to counteract the progression of malignant melanoma." (PMID 23785295, 2013). "However, the expression of vimentin is not differential significantly between primary melanomas with lymph nodes metastasis (16/28, 57.14%) with non-lymph nodes metastasis (21/42, 50%)." (PMID 20701774, 2010). "However, vimentin positivity can distinguish melanoma from undifferentiated carcinoma, but not from lymphoma or sarcoma." (PMID 18445301, 2008). "In addition, analysis of E-cadherin, Vimentin, CD80, and CD155 proteins in cSCC patient samples shows their value as predictive biomarkers of anti-PD-1/PD-L1 response, which has also been corroborated in head and neck squamous cell carcinoma (HNSCC) and melanoma patient samples." (PMID 38914547, 2024). "We also tested the modulators of the EMT pathway (spectralflow cytometry of vimentin and MCAM and CD44 expression) to figureout differences between BRAF and non-BRAF positive melanoma cell linesusing large tumorspheres." (PMID 40621031, 2025). "Positive immunoreactivity for vimentin, S-100 and NSE along with a negative cytokeratin immunoreactivity supports a melanoma diagnosis." (PMID 34822634, 2021). "Melanoma, on the other hand, is typically positive for c-kit, CD68, S-100, HMB-45, Melan-A, throsinase, and vimentin, and negative for smooth muscle actin, desmin, chromogranin, and epithelial membrane antigen." (PMID 33478436, 2021). "With regards to IHCs, most melanomas, including HWDMN, are cytokeratin negative and vimentin positive, but sarcomas can have similar staining patterns." (PMID 34822634, 2021). "On IHC, tumour cells were positive for S-100 and vimentin, while negative for cytokeratin, epithelial membrane antigen (EMA), desmin, CD34, Melan-A, and human melanoma black (HMB-45)." (PMID 33520482, 2020). "In melanoma, CSDE1 promotes translation elongation of VIM without altering its steady-state transcript levels." (PMID 29129916, 2017). "Undifferentiated melanomas are defined as completely lacking conventional histopathological and immunohistochemical melanocytic differentiation (negative for the five commonly used melanoma markers—MelanA, MiTF, HMB45, S100, and SOX10) and displaying a “vimentin-only” phenotype." (PMID 37373134, 2023). "Both melanoma and normal skin-derived cell populations express the fibroblastic marker FSP-1 (Fibroblast Specific Protein-1) and the mesenchymal marker vimentin, but not the epithelial marker E-cadherin, the endothelial marker CD31, the hematopoietic marker CD34 or the leukocyte marker CD45." (PMID 28423623, 2017).